IL34 (interleukin 34)
Diseases named in the same sentence as IL34 in open-access papers (continued):
Sharing a sentence is not in itself a finding about the gene and the disease.
Sepsis (continued). "Our study specifically focuses on interleukin 34 (IL-34) due to its novel role in regulating immune responses, particularly in the context of sepsis." (PMID 40176879, 2025). "To further investigate the relationship between IL-34 and sepsis-induced ALI, we excluded five patients with lung injuries due to other causes." (PMID 40176879, 2025). "IL-34 concentration was significantly elevated in human sepsis and puncture-induced experimental sepsis." (PMID 35563475, 2022). "In mice with cecal ligation and puncture- (CLP-) induced sepsis, treatment with IL-34 has been found to significantly reduce macrophage infiltration, protect against organ injury, and improve survival, while neutralization of IL-34 exerts the opposite effects." (PMID 33628366, 2021). "Reportedly, treatment with IL-34 also assisted to protect mice against polymicrobial sepsis by inducing the expression of cytokines (IL-6, TNFα) and chemokines (CXCL1, CCL2)." (PMID 32231137, 2020). "The primary objective of this study was to determine whether IL-34 can predict outcomes in ICU patients suffering from sepsis and sepsis-induced ALI." (PMID 40176879, 2025). "Additionally, IL-34 levels exhibited a positive correlation with sepsis severity, as indicated by APACHE II and SOFA scores." (PMID 40176879, 2025). "We hypothesized that elevated levels of IL-34 would correlate with the severity of sepsis and sepsis-induced ALI, thereby serving as a reliable prognostic marker." (PMID 40176879, 2025). "Rather, it sought to investigate the novel and underexplored role of IL-34 in sepsis." (PMID 40176879, 2025). "Therefore, this study aimed to investigate the potential of IL-34 as a biomarker for both sepsis and sepsis-induced ALI." (PMID 40176879, 2025). "Consequently, we further categorized sepsis patients to explore the relationship between serum IL-34 and prognostic outcomes in those with ALI." (PMID 40176879, 2025). "The next cytokine that affects phagocytosis during sepsis is IL-34." (PMID 35563475, 2022). "Similarly, we explored the relationship between IL-34 and prognosis in sepsis patients." (PMID 40176879, 2025). "However, the prognostic value of IL-34 in sepsis-induced ALI requires further investigation." (PMID 40176879, 2025). "This study found that IL-34 is highly expressed in sepsis group and non-survival group, with expression levels correlating with disease severity." (PMID 40176879, 2025). "IL-34, SOFA score, and their combined prognostic value in sepsis." (PMID 40176879, 2025). "Currently, there is limited direct data regarding the relationship between IL-34 and sepsis patients, and no reports have been published on the role of IL-34 in patients with sepsis-induced ALI." (PMID 40176879, 2025). "Furthermore, we did not evaluate the dynamic changes of IL-34 in all sepsis patients." (PMID 40176879, 2025).
synovitis (6 papers, 2015 to 2023). Inflammation of a synovial membrane. "The expression of IL-34 is closely associated with inflammation, leukocyte count, and severity of synovitis in patients." (PMID 37175932, 2023). "Our subsequent analysis further uncovered the positive associations of IL-34 mRNA and protein expressions with the severity of knee OA synovitis." (PMID 32409720, 2020). "In knee OA synovium with severe synovitis, increased IL-34 mRNA expression was directly associated with IL-6, IκB, NF-κB, and MMP-13, in addition to knee OA FLS." (PMID 32409720, 2020). "Accordingly, the present study aimed to investigate transcriptional and translational expressions of IL-34 in knee OA synovium and determine the possible associations of its mRNA and protein expressions with the degree of synovitis." (PMID 32409720, 2020). "Additionally, IL-34 expression and production in the systemic and local joint environments were found to be positively associated with the severity of knee OA synovitis." (PMID 32409720, 2020). "Increments in joint fluid and plasma IL-34 levels in knee OA patients with severe synovitis were closely related to its mRNA and protein expressions in knee OA synovium." (PMID 32409720, 2020). "Further investigations are still essential for better understanding of IL-34 exact role in the pathogenesis of knee OA synovitis, which would open novel therapeutic opportunities." (PMID 32409720, 2020). "Transcriptional and translational expressions of IL-34 were positively correlated with synovitis severity." (PMID 32409720, 2020). "Altogether, plasma IL-34 appears to have potential as a non-invasive biomarker indicating the development and progression of knee OA synovitis." (PMID 32409720, 2020). "In joint fluid and plasma of knee OA, IL-34 levels were observed to be positively correlated with the degree of synovitis (r = 0.65, P < 0.001; r = 0.74, P < 0.001, respectively)." (PMID 32409720, 2020). "Subsequent analysis disclosed increases in synovial fluid and plasma IL-34 levels in knee OA patients with severe synovitis." (PMID 32409720, 2020). "In the synovial sub-lining layer of knee OA, IL-34 protein expression was significantly higher in knee OA synovium with high-grade synovitis than in those with low-grade synovitis (P < 0.001) and without synovitis (P < 0.001)." (PMID 32409720, 2020). "Due to lack of reliable and specific biomarkers for knee OA synovitis, the AUC of the ROC curve was constructed to determine the possibility whether plasma IL-34 could be employed as a useful biomarker for the developmental synovitis." (PMID 32409720, 2020). "Firstly, the causal associations of IL-34 mRNA and protein expressions with the severity of knee OA synovitis were not fully addressed in the study, because of the cross-sectional design with relatively small numbers of study participants." (PMID 32409720, 2020). "In order to estimate expression levels of IL-34 protein in knee OA synovium among different synovitis groups, the staining intensity and percentage of IL-34 positive cells were assessed by a visual scoring method represented as a total score of staining on histological sections of the synovium." (PMID 32409720, 2020). "Given that transcriptional and translational overexpressions of IL-34 have been delineated in knee OA FLS treated with TNF-α and the inflamed synovium, whether its levels in the synovial fluid and circulation are associated with the severity of knee OA synovitis was determined in the current study." (PMID 32409720, 2020). "Quantitative real-time PCR showed that relative IL-34 mRNA expression was significantly higher in knee OA synovium with severe synovitis than that in those with mild synovitis (P = 0.017) and no synovitis (P < 0.001)." (PMID 32409720, 2020). "Correspondingly, knee OA synovium with mild synovitis remained remarkably more pronounced IL-34 mRNA expression, as compared with those without synovitis (P < 0.001)." (PMID 32409720, 2020).
synovitis (continued). "In contrast to this, IL-34 was scarcely expressed in knee OA synovium without synovitis, being demonstrated as faint cytoplasmic staining." (PMID 32409720, 2020). "Immunostaining score of IL-34 was considerably greater in knee OA synovium with severe synovitis than that in those with mild and no synovitis." (PMID 32409720, 2020). "Furthermore, transcriptional and translational levels of IL-34 were significantly elevated in knee OA synovium with severe synovitis, compared with those with mild and no synovitis." (PMID 32409720, 2020).
acute myeloid leukemia (5 papers, 2023 to 2025). Acute myeloid leukemia (AML) is a group of neoplasms arising from precursor cells committed to the myeloid cell-line differentiation. "Here MLL-AF9 induced mouse acute myeloid leukemia (AML) model overexpressing IL-34 (MA9-IL-34) was used to explore its role in AML." (PMID 37149693, 2023). "Besides, in acute myeloid leukemia (AML), TREM2, as a novel receptor for IL-34, can induce myeloid differentiation and inhibit AML progression by inhibiting the ERK1/2/Rasal3 signaling pathway." (PMID 38725629, 2024).
diabetes (5 papers, 2016 to 2023). "In addition, Polish studies have shown that IL-34 can be used as a potential inflammatory biomarker for predicting the risk of diabetes complications." (PMID 34095310, 2021).
lung adenocarcinoma (5 papers, 2015 to 2021). A carcinoma that arises from the lung and is characterized by the presence of malignant glandular epithelial cells. "Similar with IL-34, M-CSF expression was detected in lung adenocarcinomas (ADCs), squamous cell carcinomas (SCCs) and small cell lung cancers (SCLCs) with a variety among patients." (PMID 29323162, 2018). "Moreover, in lung adenocarcinoma, IL-34 protein levels increased upon treatment with doxorubicin and cisplatin, suggesting a possible regulation of IL-34 in response to therapy." (PMID 34535634, 2021). "However, the potential mechanism and prognostic value of IL-34 in lung adenocarcinoma (LUAD) remain obscure." (PMID 34336646, 2021). "Moreover, as the expression of both IL-34 and M-CSF1-R in primary lung adenocarcinoma cells increases upon exposure to doxorubicin or cisplatin, IL-34 protein levels may also serve as a biomarker to monitor chemoresistance insurgence and progression in cancer patients receiving chemotherapy." (PMID 31968663, 2020).
lupus nephritis (5 papers, 2018 to 2024). Glomerulonephritis in the context of systemic lupus erythematosus. "More recently, IL-34 has been suggested to be highly expressed in human mesangial cells of lupus nephritis patients and is negatively regulated by the Wnt pathway." (PMID 33072227, 2020).
atopic dermatitis (4 papers, 2015 to 2022). "Interestingly, IL-34 expression in skin was decreased in lesional skin of AD (atopic dermatitis) patients, described to be related to the skin barrier, which is affected in AD." (PMID 25896238, 2015). "In allergic dermatitis, the expression of IL-34 in the skin tissue of patients with skin lesions was significantly lower than that in patients without skin lesions, and the number of Langerhans cells was also significantly reduced, indicating IL-34 may be an indicator of tissue damage." (PMID 30405534, 2018).
Autoimmunity (4 papers, 2016 to 2025). The occurrence of an immune reaction against the organism's own cells or tissues. "A previous analysis of the phenotype of an Il34 mutation in rats was focussed on the putative expression of IL34 by regulatory T cells (Treg) and a role in autoimmunity." (PMID 40533345, 2025). "Thus, altogether, IL‐34 deficiency in mice leads to an unstable immune phenotype, with increase susceptible to autoimmunity and inflammation in a specific environment." (PMID 36030499, 2022). "Altogether, our study emphasizes the crucial role of IL‐34 for immune homeostasis and for CD4+ Tregs suppressive function and the therapeutic potential of IL‐34 in human transplantation and autoimmunity." (PMID 36030499, 2022). "Their focus was on the proposed function of IL34 in control of autoimmunity." (PMID 40533345, 2025). "We hypothesized that vitamin D signaling in neurons may promote IL-34 production that helps prevent excessive microglia activation during inflammation in early life, making the CNS less vulnerable to CNS autoimmunity." (PMID 32082243, 2020). "Thus, the contribution of IL‐34 in immune homeostasis, Treg function, as well as its role in autoimmunity and human transplant rejection remains unclear and needs to be further addressed." (PMID 36030499, 2022).
cervical cancer (4 papers, 2021 to 2026). A primary or metastatic malignant neoplasm involving the cervix. "We therefore hypothesized that a reduction in IL34 might be associated with poorer outcome in cervical cancer patients." (PMID 34805788, 2021). "Importantly, the disruption of IL34-mediated keratinocyte-LC interactions may be clinically important in human cervical cancer, as low IL34 expression in cancer biopsies was associated with a worse prognosis." (PMID 34805788, 2021). "Our previous research has identified IL34 as a dysregulated and prognosis‐associated gene in CIN and cervical cancer." (PMID 41362277, 2026). "Importantly, we here highlight the clinical significance of low IL34 expression, as it correlates with poor survival in cervical cancer patients, in HNSCC and in lung SCC." (PMID 39619016, 2024). "The enriched genes included CD4 in cervical cancer, VPS52, NUP62, CRYGD, IL34, GATA3 in prostate cancer and F11, TXNIP, KIT, ASGR2, SERPINF1 in liver cancer, which also provide insight into the molecular mechanisms underlying cancer progression and the potential impact on patient survival." (PMID 37393582, 2023).
chronic kidney disease (4 papers, 2016 to 2025). Impairment of the renal function secondary to chronic kidney damage persisting for three or more months. "To determine the role of IL34 in chronic renal inflammation, we established the rat adenine diet model, which leads to slowly progressive kidney damage with many features of chronic kidney disease in humans including tubular atrophy, interstitial fibrosis, and glomerulosclerosis." (PMID 40533345, 2025).
Cirrhosis (4 papers, 2016 to 2023). A chronic disorder of the liver in which liver tissue becomes scarred and is partially replaced by regenerative nodules and fibrotic tissue resulting in loss of liver function. "Interestingly, a close correlation is observed between IL-34 and M-CSF in liver injury among chronic hepatitis C patients who had high fibrosis scores and possibly cirrhosis." (PMID 36438052, 2022). "This notion is supported by observations of significantly higher intra-hepatic IL-34 detected in HBV induced HCC patients, compared non-cancer or chronic hepatitis B or hepatitis B viral induced-cirrhosis patients, particularly that IL-34 is localized in the cytoplasm of hepatocytes of HCC." (PMID 36438052, 2022). "Furthermore, serum IL-34 is correlated with hepatic inflammation and fibrosis in chronic hepatitis B patients, which are considered to be major markers of the development of cirrhosis and liver malignancy." (PMID 36438052, 2022). "Circulating IL-34 of HBV-HCC patients was significantly higher than that of CHB, HBV-cirrhosis and HCs." (PMID 35347503, 2023). "Serum IL-34 was 1.7, 1.3 or 2.3-fold higher in HBV-HCC than that of CHB, HBV related cirrhosis or healthy control, which was inhibited following trans-hepatic arterial chemoembolization (TACE) in HBV-HCC patients." (PMID 35347503, 2023). "Consistent with circulating IL-34, upregulated intra-hepatic IL-34 from HBV-HCC was also detected, compared to that of CHB, HBV-cirrhosis and HCs." (PMID 35347503, 2023). "Circulating and intra-hepatic IL-34 was upregulated gradually in HBV disease progression from CHB, cirrhosis and HCC." (PMID 35347503, 2023). "Serum IL-34 was 1.7, 1.3 or 2.3-fold higher from HBV-HCC groups than that from CHB (35.74 vs. 21.22, p < 0.01), HBV-cirrhosis (35.74 vs. 26.58, p < 0.05) or HCs (35.74 vs. 15.71, p < 0.01)." (PMID 35347503, 2023). "Intra-hepatic IL-34 and MCSF from HBV-HCC patients were significantly higher than that of CHB, HBV-cirrhosis and HCs (p < 0.05)." (PMID 35347503, 2023). "Serum IL-34 levels, as well as M-CSF, sCD163, APRI, and FIB-4 index, were also elevated in HCV-positive patients with advanced fibrosis/cirrhosis (≥Stage 3)." (PMID 27363523, 2016). "Our study identified circulating IL-34 from HBV-HCC patients was significantly higher than that of CHB, HBV-cirrhosis and HCs, suggesting that IL-34 may contribute to tumorigenesis of HCC, enhancing progression from CHB patients to cirrhosis, and finally HCC." (PMID 35347503, 2023). "According to our results, cirrhosis status did not have significant effect on IL-34 expression." (PMID 28614380, 2017). "In order to clarify the impact of disease progression on IL-34 levels, we divided HBV patients into two groups (With or Without cirrhosis) based on pathological findings and further compared the serum IL-34 levels between those two groups." (PMID 28614380, 2017).
cognitive decline (4 papers, 2021 to 2025). "Elevated salivary IL-34 and CSF-1 levels in AD and MCI patients suggest an inflammatory component linked to cognitive decline." (PMID 40389754, 2025). "The KO caused a significant increase in IL-34, TREM2, and β-Catenin gene expression together with the improvement of cognitive decline and a decrease in Aβ burden." (PMID 33402196, 2021). "Furthermore, salivary interleukin-34 (IL-34) levels are elevated in AD patients and are inversely associated with Mini-Mental State Examination (MMSE) scores, indicating a potential role in cognitive decline." (PMID 41471945, 2025). "Indeed, TREM2/β-Catenin and IL-34 expression increase leading to a reduction of plaque volume and a delayed cognitive decline." (PMID 33402196, 2021). "Furthermore, Mizuno and colleagues demonstrated that injections of IL-34 ameliorate cognitive decline and reduce Aβ burden in APP/PS1 mice." (PMID 33402196, 2021).
fibrosis (4 papers, 2016 to 2025). the formation of excess fibrous connective tissue in an organ or tissue in a reparative or reactive process. "The reasons for the close association of IL-34 with fibrosis in NAFLD, as we found in this study, remain largely unknown." (PMID 27363523, 2016). "We then examined in vivo CD8 T cells in the liver of the TAA-induced fibrosis model treated with IL-34 + IL-4 Mf." (PMID 39856797, 2025). "The AUC, sensitivity, and specificity of IL-34-FS were 0.86, 75.2, and 85.0% (significant fibrosis), 0.88, 81.7, and 79.4% (advanced fibrosis), and 0.94, 83.3, and 85.6% (liver cirrhosis) respectively." (PMID 29201774, 2017).